ZNF563 (zinc finger protein 563)
Description:
May be involved in transcriptional regulation.
Synonyms: FLJ34797
Tractability: PROTAC: ubiquitination databases record sites on it.
Gene: Protein-coding gene on chromosome 19 (12,317,477 to 12,333,720, reverse strand). Ensembl gene ENSG00000188868.
Subcellular location: Nucleus
Subcellular location (Human Protein Atlas): Vesicles
Pathways (Reactome):
Gene expression (Transcription): Generic Transcription Pathway
Gene Ontology:
Molecular function: protein binding; DNA-binding transcription factor activity, RNA polymerase II-specific; RNA polymerase II transcription regulatory region sequence-specific DNA binding
Biological process: regulation of transcription by RNA polymerase II; regulation of DNA-templated transcription
Cellular component: nucleus
Genetic constraint (gnomAD): Loss-of-function variants: 34 observed, 45.19 expected, observed/expected ratio (o/e) 0.75, 90% interval 0.57 to 1. The upper end of that interval is the gene's LOEUF score, 1, which puts it in group 4 of 6, group 1 being the genes least tolerant of losing a copy. Missense variants: 511 observed, 603.3 expected, observed/expected ratio (o/e) 0.85, 90% interval 0.79 to 0.91. Synonymous variants: 165 observed, 193.15 expected, observed/expected ratio (o/e) 0.85, 90% interval 0.75 to 0.97.
Homologues: Orthologues: chimpanzee ZNF563 (99% identical), mouse Zfp961 (32% identical), rat Zfp617 (32% identical). Paralogues in human: ZNF443 (75% identical), ZNF799 (75% identical), ZNF44 (73% identical), ZNF823 (71% identical), ZNF442 (69% identical), ZNF441 (62% identical), ZNF709 (55% identical), ZNF700 (53% identical), ZNF433 (53% identical), ZNF14 (50% identical), ZNF791 (49% identical), ZNF844 (47% identical), and 3 more.
Diseases named in the same sentence as ZNF563 in open-access papers:
ZNF563 is named in the same sentence as 2 diseases in open-access papers, as found by Europe PMC text mining. Sharing a sentence is not in itself a finding about the gene and the disease.
ZNF563 shares sentences with these, for which no sentence is quoted: Immunodeficiency (1 paper); neurologic diseases (1).